SNORA5B (small nucleolar RNA, H/ACA box 5B)
Synonyms: ACA5b
Gene: Small nucleolar RNA gene on chromosome 7 (45,105,968 to 45,106,099, reverse strand). Ensembl gene ENSG00000200656.
Gene Ontology:
Biological process: RNA processing
Cellular component: nucleolus
Homologues: Orthologues: chimpanzee SNORA5B (98% identical), macaque SNORA5B (95% identical). Paralogues in human: SNORA5A (91% identical), SNORA5C (64% identical).